LRRC19 (leucine rich repeat containing 19)
Description:
Pathogen-recognition receptor which mediates the activation of TRAF2- and TRAF6 NF-kappa-B signaling pathways and induces the expression of pro-inflammatory cytokines. In kidney, prevents infection by uropathogenic bacteria by inducing the production of cytokines, chemokines and antimicrobial substances. In gut, involved in host-microbiota interactions, plays a critical role in promoting the recruitment of immune cells and intestinal inflammation (By similarity).
Synonyms: FLJ21302
Tractability: Antibody: UniProt predicts a signal peptide or a membrane-spanning region; its Gene Ontology location is reachable by antibodies, with medium confidence.
Gene: Protein-coding gene on chromosome 9 (26,993,136 to 27,005,709, reverse strand). Ensembl gene ENSG00000184434.
Subcellular location: Membrane
Gene Ontology:
Molecular function: protein binding; signaling receptor activity
Biological process: positive regulation of non-canonical NF-kappaB signal transduction; host-mediated modulation of intestinal microbiota composition; positive regulation of canonical NF-kappaB signal transduction; regulation of cytokine production; regulation of inflammatory response; toll-like receptor signaling pathway
Cellular component: plasma membrane; membrane
Genetic constraint (gnomAD): Loss-of-function variants: 16 observed, 24.43 expected, observed/expected ratio (o/e) 0.66, 90% interval 0.44 to 1. The upper end of that interval is the gene's LOEUF score, 1, which puts it in group 4 of 6, group 1 being the genes least tolerant of losing a copy. Missense variants: 372 observed, 344.34 expected, observed/expected ratio (o/e) 1.08, 90% interval 0.99 to 1.18. Synonymous variants: 151 observed, 128.79 expected, observed/expected ratio (o/e) 1.17, 90% interval 1.03 to 1.34.
Homologues: Orthologues: chimpanzee LRRC19 (99% identical), macaque LRRC19 (95% identical), dog LRRC19 (79% identical), pig LRRC19 (79% identical), rabbit LRRC19 (78% identical), guinea pig LRRC19 (76% identical), mouse Lrrc19 (70% identical), rat Lrrc19 (69% identical). Paralogues in human: FLRT1 (25% identical), FLRT3 (22% identical), LRRTM4 (22% identical), FLRT2 (21% identical), LRRTM3 (21% identical), LRRC4 (21% identical), LRRC4C (20% identical), LRRC66 (19% identical), LRRC4B (19% identical), GP1BA (19% identical), LRRTM1 (18% identical), LRTM1 (18% identical), and 10 more.
Diseases named in the same sentence as LRRC19 in open-access papers:
LRRC19 is named in the same sentence as 33 diseases in open-access papers, as found by Europe PMC text mining. Sharing a sentence is not in itself a finding about the gene and the disease. The quoted sentences say what the papers report.
colitis (4 papers, 2016 to 2024). Inflammation of the colon. "All of these data imply that LRRC19 is associated with enteritis, colitis, and colitis-associated tumorigenesis." (PMID 26776522, 2016). "On the other hand, a decreased susceptibility to colitis was observed in Lrrc19−/− mice." (PMID 38172943, 2024). "The results showed that LRRC19 deficiency conferred a marked resistance to DSS-mediated colitis." (PMID 26776522, 2016). "Taken together with in vitro observations, these results confirm that DVF-mediated exacerbation of colitis is dependent on activation of LRRC19 signaling." (PMID 38172943, 2024). "These extra chemokines also increased the sensitivity to DSS-mediated colitis in Lrrc19 KO mice and in WT mice." (PMID 26776522, 2016). "We next used dextran sodium sulfate (DSS)-induced colitis and an azoxymethane (AOM)-DSS-induced colon cancer model to examine the effects of LRRC19 on the occurrence and development of colitis and colon cancer." (PMID 26776522, 2016). "Colitis-associated phospho-nuclear factor κB (NF-κB) p65, and -STAT3, which were detected readily in WT mice, were barely detectable in Lrrc19 KO mice." (PMID 26776522, 2016). "Considering the crucial role of LRRC19 in gut host-microbiota interaction, we sought to investigate whether Desulfovibrio vulgaris (D. vulgaris) or D. vulgaris flagellin (DVF) could interact with LRRC19 and exacerbate colitis." (PMID 38172943, 2024). "Our data indicated the flagellin of D. vulgaris could interact with LRRC19 and thus accelerate colitis, suggesting a key role of D. vulgaris in the pathogenesis of UC." (PMID 38172943, 2024). "Compared with PBS-treated colitis mice, the expression of LRRC19 was upregulated in DVF groups." (PMID 38172943, 2024). "In addition, DEGs associated with the immune receptor (Lrrc19), cell chemotaxis (Ccr7, Cxcl1, Cxcl5, Cxcl9, and Cxcl10), and inflammatory response (IL1r11, IL11, Tnf, IL1β, and IL18) were also upregulated in the colonic tissue of colitis mice in DVF group." (PMID 38172943, 2024). "Animal experiments have demonstrated LRRC19 may participate in the pathogenesis of colitis." (PMID 38172943, 2024). "Although WT mice showed clear symptoms of colitis after exposure to 2.0% DSS in their drinking water for 7 days, the colitis symptoms, including survival rate, weight loss, colon shortening, and histology scores, were suppressed significantly in the cohoused Lrrc19 KO mice." (PMID 26776522, 2016). "Confocal immunostaining showed that the colocalization between LRRC19 and TRAF6 in DVF-treated colitis mice was highly visible, but colocalization of LRRC19 and TRAF2 was rarely observed." (PMID 38172943, 2024). "To further confirm the role of LRRC19 in DVF-mediated inflammation, we then treated colon organoids derived from colitis mice (Lrrc19−/− mice) with DVF or PBS." (PMID 38172943, 2024). "Associated study also showed that flagellin from Desulfovibrio vulgaris (DVF), the representative bacterium of the Desulfovibrio genus, could exacerbate colitis due to the interaction of DVF and LRRC19, leading to the secretion of pro-inflammatory cytokines." (PMID 39060944, 2024). "Since LRRC19 and its downstream pro-inflammatory chemokines were upregulated after DVF treatment in colitis, we hypothesized that DVF can activate LRRC19 and thus contribute to colonic inflammation." (PMID 38172943, 2024). "To validate DVF could activate LRRC19 signaling in vivo, we investigated the activation of LRRC19 pathway in DVF-treated colitis mice." (PMID 38172943, 2024). "Mechanistically, DVF could interact with LRRC19 (rather than TLR5) in colitis mice and organoids, and then induce the production of pro-inflammatory cytokines." (PMID 38172943, 2024). "However, typhaneoside treatment had no directly inhibitory effect on LRRC19 expression in colitis mice." (PMID 38172943, 2024). "Besides, we found DVF challenge did not promote apoptosis in the organoids derived from colitis mice (Lrrc19−/− mice)." (PMID 38172943, 2024).
colitis (continued). "Moreover, a recent study also showed that D. vulgaris flagellin (DVF) could exacerbate colitis due to the interaction of DVF and LRRC19, leading to the secretion of pro-inflammatory cytokines." (PMID 39060944, 2024). "Interestingly, when the gut tissues of these mice were examined, almost all WT mice showed slight inflammation (low-grade enteritis and colitis) whereas Lrrc19 KO mouse gut tissues did not." (PMID 26776522, 2016). "In the present study, although typhaneoside treatment did not significantly improve DSS colitis in mice, we found typhaneoside can prevent DVF-mediated activation of LRRC19 signaling and exacerbation of colonic inflammation." (PMID 38172943, 2024). "Mice were treated with dextran sulfate sodium to induce colitis with or without administration of D. vulgaris or D. vulgaris flagellin (DVF), and the severity of colitis and the leucine-rich repeat containing 19 (LRRC19) signaling were assessed." (PMID 38172943, 2024).
colorectal cancer (3 papers, 2022 to 2025). A primary or metastatic malignant neoplasm that affects the colon or rectum. "Moreover, Desulfovibrio vulgaris flagellin exacerbates colorectal cancer epithelial–mesenchymal transition via LRRC19/TRAF6/TAK1 signaling pathway activation, promoting tumor growth." (PMID 41471248, 2025). "Furthermore, we collected tumor samples from patients with colorectal cancer and normal tissues adjacent to the tumor for pathological sections and used immunohistochemistry to evaluate the expression of LRRC19 in colorectal cancer." (PMID 35794979, 2022).
pancreatic cancer (3 papers, 2012 to 2022). "Unfortunately, for these reasons, conclusions cannot be made about the LRRC19 > IGFBP2 classifier as a predictor for Src sensitivity in patients with advanced pancreas cancer in this trial." (PMID 23342270, 2012). "Additionally, LRRC19 mRNA expression was lower in breast cancer, cervical cancer, kidney cancer, and pancreatic cancer." (PMID 35794979, 2022). "LRRC19 has been reported to be involved in kidney and skin inflammatory response and as a potential biomarker in KIRC and pancreatic cancer." (PMID 32316597, 2020).
breast carcinoma (2 papers, 2017 to 2022). "The Kaplan–Meier plotter survival analysis indicated that low LRRC19 expression was significantly associated with the disease progression of patients with ovarian cancer, gastric cancer, breast cancer, and lung cancer." (PMID 35794979, 2022). "To further evaluate the prognostic potential of LRRC19 in different cancers, we used the Kaplan–Meier plotter database to evaluate the LRRC19 prognostic significance in four types of cancer, including breast cancer, ovarian cancer, lung cancer, and gastric cancer." (PMID 35794979, 2022). "Of note, the diminished expression of putative hub genes such as CDKN2B, CNNM4, LRRC19, and MOGAT2 might be the result of inactivation of genes through DNA methylation as their methylation was identified in colorectal, gastric, and breast cancers as well as in leukaemia." (PMID 29088818, 2017).
pressure ulcers (2 papers, 2020 to 2022). "LRRC19 was also mentioned for its therapeutic potential in pressure ulcers, by promoting NF-kB-dependent pro-inflammatory response." (PMID 35794979, 2022). "LRRC19 was also reported for its therapeutic potential for pressure ulcers, by promoting NF-κB dependent pro-inflammatory response." (PMID 32316597, 2020).
acute myeloid leukemia (1 paper, 2020). Acute myeloid leukemia (AML) is a group of neoplasms arising from precursor cells committed to the myeloid cell-line differentiation. "The differential expression of LRRC19 was observed to be downregulated in Kidney Chromophobe (KICH) and KIRC and upregulated in Acute Myeloid Leukemia (LAML)." (PMID 32316597, 2020).
clear cell renal cell carcinoma (1 paper, 2020). "In conclusion, low expression of LRRC19 was identified as an independent risk factor, which will advance our understanding concerning the selenium adjuvant therapy of clear cell renal cell carcinoma." (PMID 32316597, 2020). "The loss of chromosomal region 9p24.1-p13.3 is implicated in metastatic clear cell renal cell carcinoma, and LRRC19 was significantly more downregulated in primary tumors with gene copy number loss than in those without it." (PMID 32316597, 2020). "Gene set enrichment analysis (GSEA) identified tyrosine metabolism, metabolic pathways, peroxisome, and fatty acid degradation as differentially enriched with the high LRRC19 expression in KIRC cases, which are involved in selenium therapy of clear cell renal cell carcinoma." (PMID 32316597, 2020).
colon cancer (1 paper, 2016). "β-Catenin and cyclooxygenase 2 (COX2), colon cancer-associated markers, were also detected more readily in WT mice compared with Lrrc19 KO mice." (PMID 26776522, 2016). "The colon cancer-associated markers proliferating cell nuclear antigen (PCNA) and COX2 were also difficult to detect in Lrrc19 KO mice." (PMID 26776522, 2016). "In the AOM-DSS-induced colon cancer model, WT mice developed a high incidence of colon tumors in the distal to middle colon, whereas no tumors were found in cohoused Lrrc19 KO mice treated with the same protocol." (PMID 26776522, 2016).
esophageal carcinoma (1 paper, 2022). A primary or metastatic malignant neoplasm involving the esophagus. "Nevertheless, LRRC19 expression was obviously higher in esophageal carcinoma (ESCA), head and neck cancer (HNSC), and stomach adenocarcinoma (STAD) compared with adjacent normal tissues." (PMID 35794979, 2022).
lung carcinoma (1 paper, 2022). "However, low LRRC19 expression was correlated with a better prognosis of FP in lung cancer." (PMID 35794979, 2022).
selenium deficiency (1 paper, 2020). A nutritional deficiency disease resulting from inadequate selenium levels in the body, which can lead to impaired function of selenoproteins essential for antioxidant defense and thyroid hormone metabolism. "Our analysis assumes that KIRC patients were generally in a low selenium state, and the gene expression of LRRC19 in KIRCs and adjacent tissues might both be affected by selenium deficiency to some extent." (PMID 32316597, 2020).
Stroke (1 paper, 2019). Sudden impairment of blood flow to a part of the brain due to occlusion or rupture of an artery to the brain. "LRRC19 encodes a protein with a potential role in regulating neurite outgrowth, and might thus influence stroke recovery." (PMID 30796134, 2019).
tumor (4 papers, 2012 to 2025). "We also did survival analysis of LRRC19, taking into account important covariates such as patient’s age and gender, tumor’s grade, and other clinical factors available for the TCGA cohort." (PMID 32316597, 2020). "We picked out LRRC19 as a potential tumor suppressor gene for its significant downregulation of mRNA levels in CRC tissues, as well as its largely unknown status in most of the tumors including CRC." (PMID 35794979, 2022). "Furthermore, LRRC19 is involved in a number of molecular functions related to tumor progression, such as protein serine/threonine phosphatase inhibitor activity and superoxide-generating NAD(P)H oxidase activity." (PMID 35794979, 2022). "The results of the functional enrichment pathway and PPI analyses suggest that LRRC19 might be a tumor suppressor gene." (PMID 35794979, 2022). "Based on the expanded correlation analysis results, we found that ACOX1, ALDH2, FUT6, and LRRC19 have a high association with GPX3 and DIO1 in the TCGA database, whether it is only tumor samples or “tumor samples + normal samples”." (PMID 32316597, 2020). "Therefore, prior to treatment, archival tumor tissue or fresh tumor biopsies were tested for the biomarker 1 (LRRC19 > IGFBP2) and/or biomarker 2 (PIK3CA mutant) to determine eligibility for the study in CLIA-approved space." (PMID 23342270, 2012). "To explore whether GPX3, DIO1, and LRRC19 still correlate when including the normal tissue samples, we performed correlation analysis in the datasets of “523 TCGA tumor cases + 72 TCGA normal cases” and “523 TCGA tumor cases + 72 TCGA normal cases + 28 GTEx Kidney-Cortex cases”." (PMID 32316597, 2020). "They further performed a biomarker study for LRRC19 > IGFBP2, with a total of 47 patient tumor tissues from 10 different sites." (PMID 32316597, 2020). "Meanwhile, no important correlation was discovered between LRRC19 expression and other clinicopathological features, including age (P=0.589), gender (P=0.278), tumor location (P=0.399), pathology stage (P=0.104), and M stage (P=0.211)." (PMID 35794979, 2022).
cancer (2 papers, 2020 to 2022). A tumor composed of atypical neoplastic, often pleomorphic cells that invade other tissues. "To further assess LRRC19 expression in human cancers, we detected LRRC19 expression using the TIMER database." (PMID 35794979, 2022). "As the only intersection gene with significant differential expression and prognostic value, we also performed the survival analysis and gene expression of LRRC19 in 33 cancer types of TCGA." (PMID 32316597, 2020). "In addition, increased or decreased LRRC19 expression has different prognostic effects according to the cancer type." (PMID 35794979, 2022).
infection (1 paper, 2016). The state of being infected such as from the introduction of a foreign agent such as serum, vaccine, antigenic substance or organism. "LRRC19-expressing adenovirus was injected intraperitoneally three times per week, with demonstrable infection." (PMID 26776522, 2016).
inflammation (1 paper, 2024). Aberrant reaction of the microcirculation characterized by movement of fluid and leukocytes from the blood into extravascular tissues. "Depletion of LRRC19 or blocking the DVF-LRRC19 interaction by typhaneoside, a flavonoid glycoside, significantly attenuated DVF-mediated intestinal inflammation." (PMID 38172943, 2024).
LRRC19 also shares sentences with these, for which no sentence is quoted: colon adenocarcinoma (2 papers); enteritis (2); lung adenocarcinoma (2); rectum adenocarcinoma (2); cervical cancer (1); cholangiocarcinoma (1); colon tumors (1); gastric cancer (1); head and neck cancer (1); Jaundice (1); kidney cancer (1); kidney chromophobe (1); leukaemia (1); lung squamous cell carcinoma (1); ovarian carcinoma (1); ovarian serous cystadenocarcinoma (1); stomach adenocarcinoma (1).